MIF (macrophage migration inhibitory factor)
Description:
Pro-inflammatory cytokine involved in the innate immune response to bacterial pathogens. The expression of MIF at sites of inflammation suggests a role as mediator in regulating the function of macrophages in host defense. Counteracts the anti-inflammatory activity of glucocorticoids. Has phenylpyruvate tautomerase and dopachrome tautomerase activity (in vitro), but the physiological substrate is not known. It is not clear whether the tautomerase activity has any physiological relevance, and whether it is important for cytokine activity.
Synonyms: GIF; GLIF; MMIF
Tractability: Small molecule: a drug acting on it is in phase 2 or 3 trials; a structure with a bound ligand is known; a high-quality ligand is known; it has a high-quality binding pocket; it belongs to a druggable protein family. Antibody: a drug acting on it is in phase 2 or 3 trials; UniProt places it where antibodies can reach, with high confidence; its Gene Ontology location is reachable by antibodies, with high confidence. PROTAC: ubiquitination databases record sites on it; its protein half-life has been measured; a small molecule that binds it is known.
Target class: Enzyme
Chemical probes: TP-010 (high quality)
Gene: Protein-coding gene on chromosome 22 (23,894,372 to 23,895,227, forward strand). Ensembl gene ENSG00000240972.
Subcellular location: Secreted; Cytoplasm
Subcellular location (Human Protein Atlas): Cytosol; Nucleoplasm; Predicted to be secreted
Pathways (Reactome):
Immune System: Gene and protein expression by JAK-STAT signaling after Interleukin-12 stimulation; Neutrophil degranulation
Hemostasis: Cell surface interactions at the vascular wall
Gene Ontology:
Molecular function: chemoattractant activity; cytokine activity; cytokine receptor binding; dopachrome isomerase activity; identical protein binding; phenylpyruvate tautomerase activity; protein binding; protease binding
Biological process: cell surface receptor signaling pathway; negative regulation of apoptotic process; negative regulation of cell migration; negative regulation of cellular senescence; negative regulation of gene expression; negative regulation of macrophage chemotaxis; positive regulation of B cell proliferation; positive regulation of cAMP/PKA signal transduction; positive regulation of cell population proliferation; positive regulation of cytokine production; positive regulation of ERK1 and ERK2 cascade; positive regulation of fibroblast proliferation; positive regulation of phosphorylation; positive regulation of tumor necrosis factor production; prostaglandin biosynthetic process; protein homotrimerization; regulation of macrophage activation; negative regulation of mature B cell apoptotic process; negative regulation of myeloid cell apoptotic process; positive chemotaxis; positive regulation of arachidonate secretion; positive regulation of chemokine (C-X-C motif) ligand 2 production; positive regulation of innate immune response; and 4 more
Cellular component: cell surface; cytoplasm; cytosol; extracellular exosome; extracellular region; plasma membrane; vesicle; ficolin-1-rich granule lumen; secretory granule lumen
Genetic constraint (gnomAD): Loss-of-function variants: 16 observed, 9.01 expected, observed/expected ratio (o/e) 1.78, 90% interval 1.13 to 1.96. That is too few expected variants to judge how well the gene tolerates losing a copy. Missense variants: 229 observed, 140.58 expected, observed/expected ratio (o/e) 1.63, 90% interval 1.46 to 1.82. Synonymous variants: 83 observed, 59.94 expected, observed/expected ratio (o/e) 1.38, 90% interval 1.16 to 1.66.
Homologues: Orthologues: chimpanzee MIF (100% identical), pig MIF (95% identical), dog MIF (94% identical), guinea pig MIF (92% identical), rabbit MIF (91% identical), mouse Mif (90% identical), rat AC127887.1 (86% identical), rat LOC120102174 (83% identical), rat Mif (77% identical), zebrafish mif (69% identical), tropical clawed frog mif (64% identical), Caenorhabditis elegans mif-1 (35% identical). Paralogues in human: DDT (34% identical), DDTL (33% identical).
Diseases named in the same sentence as MIF in open-access papers:
MIF is named in the same sentence as 631 diseases in open-access papers, as found by Europe PMC text mining. Sharing a sentence is not in itself a finding about the gene and the disease. The quoted sentences say what the papers report.
Sepsis (144 papers, 2006 to 2025). Sepsis is defined as life-threatening organ dysfunction caused by a dysregulated host response to infection. "MIF has, however, been shown to be associated with the severity of several inflammatory diseases, including sepsis, meningitis and rheumatoid arthritis." (PMID 40826444, 2025). "It presented macrophage migration inhibitory factor (MIF) as a suppressor of mitophagy through the disruption of PINK1–Parkin protein interactions in sepsis-associated acute kidney injury, thereby promoting renal damage." (PMID 40497970, 2025). "MIF regulates the immune response and is associated with many diseases including autoimmune diseases, cancer, metabolic disorders, and sepsis." (PMID 39974348, 2024). "Abnormal expression of MIF has been linked to a range of diseases, including sepsis, myocardial infarction, acute kidney injury, organ fibrosis, malignant tumors, rheumatoid arthritis, systemic lupus erythematosus, and inflammatory bowel disease." (PMID 38745657, 2024). "Several recent studies have revealed that MIF acts as a proinflammatory cytokine implicated in the pathophysiology of other inflammatory diseases, such as sepsis and autoimmune liver disease." (PMID 37645013, 2023). "Inhibiting MIF can alleviate the severity of ALI caused by sepsis, reduce inflammatory response and cell apoptosis." (PMID 38076268, 2023). "Research has shown that MIF levels are significantly elevated in patients with sepsis and that higher levels are associated with worse clinical outcomes." (PMID 38275363, 2023). "MIF (Macrophage migration inhibitory factor), associated with inflammation response, has been proved as a biomarker of sepsis, and perhaps regulate pyroptosis in sepsis-induced AKI." (PMID 35165294, 2022). "MIF plays a pathogenic role in many inflammatory diseases, including acute and chronic inflammation, sepsis." (PMID 35967416, 2022). "For example, inhibition of macrophage migration inhibitory factor (a pleiotropic cytokine and central regulator of innate immune responses increased susceptibility to infection but protected from lethal sepsis." (PMID 35990654, 2022). "Macrophage migration inhibitory factor (MIF) was implicated as a biomarker in sepsis, but its diagnostic and prognostic value has remained unclear in human studies." (PMID 33850259, 2021). "MIF has also shown to be markedly and persistently upregulated and to be associated with increased disease severity and early death in patients with sepsis." (PMID 33407905, 2021). "MIF has been implicated as playing a causative role in many disease states, including sepsis, pneumonia, diabetes, rheumatoid arthritis, inflammatory bowel disease, cancer, and inflammatory skin disease." (PMID 33407905, 2021). "MIF has been associated with multiple inflammatory pathogeneses including sepsis, asthma, arthritis, inflammatory bowel disease, malaria, and atherosclerosis." (PMID 32625208, 2020). "Although MIF has been classically associated with type 1 inflammation during microbial exposure and sepsis, more recent studies have also identified a role for this molecule in development of Th2 responsiveness to allergens." (PMID 31708913, 2019). "A nationwide pediatric sepsis cohort study has been launched in Switzerland and will address the relationship between MIF and DDT gene polymorphisms and expression levels and clinical outcome." (PMID 28179905, 2017). "Future studies should also examine associations between functional MIF polymorphisms and susceptibility to neonatal and pediatric sepsis and BPD, and severity of these diseases." (PMID 28179905, 2017). "MIF is a key mediator of severe sepsis and septic shock, and it was demonstrated that MIF levels are persistently elevated in patients with sepsis, and high MIF levels were associated with parameters of disease severity and early death." (PMID 27313864, 2016).
Sepsis (continued). "Because of its importance in acute inflammation, several groups have developed inhibitory antibodies and synthetic small molecule inhibitors of MIF, and shown that they can prevent morbidity and mortality associated with endotoxemia and sepsis." (PMID 26318747, 2015). "In this case, MIF should be considered to be an important cytokine in the dividing stages and estimating prognosis by the increase in infection rate, progression to sepsis and MODS and mortality in cases of immune deficiency caused by trauma." (PMID 23251299, 2013). "Attenuation of neutrophil infiltration, suppression of NF-κB activation, and reduced MIF production in myocardium are associated with the cardioprotective effect of HS in sepsis." (PMID 24371817, 2013). "High plasma IL-10, MIF and IL-6 levels have been associated with severity and a poorer outcome in sepsis and were chosen for the present study." (PMID 22701553, 2012). "Due to the positive correlations of TRX1 and MIF, our investigation supports a linked role of these two mediators in the pathophysiology of sepsis." (PMID 20847814, 2010). "Secondly, an evaluation of the association of the MIF polymorphisms with the survival of severe sepsis patients was performed." (PMID 19941661, 2009). "In a recent study, high plasma MIF levels were shown to be associated with early death in patients with severe sepsis." (PMID 19284533, 2009). "The relevance of MIF polymorphisms in patients with sepsis was addressed only by association studies, so far." (PMID 19941661, 2009). "Treating with MIF-antibodies in a mouse infection model decreases the sepsis shock caused by LPS." (PMID 39822305, 2025). "Comparing the signaling pathways in these two groups, it can be seen that all three pathways, GRN,CCL, and PARs, are specifically expressed in the COVID-19-associated ARDS, while BAFF, CXC, LRESITIN, CypA, and MIF are specifically expressed in the sepsis-related ARDS." (PMID 38745657, 2024). "Some studies showed that urine MIF can be an indicator of renal dysfunction associated with different diseases, but whether it has a similar indicator role in sepsis has remained unclear." (PMID 36631486, 2023). "Macrophage migration inhibitory factor (MIF) is implicated in a wide range of disease states, where elevated MIF levels are markers for tumorigenesis, sepsis, acute respiratory distress syndrome (ARDS), arthritis, colitis, and Malaria." (PMID 34760929, 2021). "Third, reduced MIF levels are associated with improved survival of septic shock, and therefore, the removal of MIF could be a new therapeutic approach for adjunctive sepsis therapy." (PMID 27313864, 2016). "CRRT with consecutive lowering of MIF levels was closely associated with survival in those patients and these preliminary results should be taken into consideration further studies to develop novel concepts of adjunctive sepsis therapy." (PMID 27313864, 2016). "Overexpression of MIF protein in sepsis causes cardiac dysfunction." (PMID 24371817, 2013). "MIF has recently become both an attractive marker for prognostic prediction and a therapeutic target, because levels of MIF are associated with the mechanisms of both inflammation and coagulation in sepsis." (PMID 20021698, 2009). "Consequently, high serum MIF is considered to be associated with insufficient activation of the HPA axis in patients with severe sepsis or septic shock." (PMID 20021698, 2009). "As a follow up to this study and given the role of MIF in sepsis associated death and other neurological disorders, we hypothesized that elevated levels of MIF may be involved in CM-associated death." (PMID 19284533, 2009). "We hypothesized that serum concentrations of MIF are associated with the changes in serum 4 cortisol that occur after ACTH stimulation in sepsis patients." (PMID 20021698, 2009). "In addition, MIF was associated with dysregulated pituitary-adrenal function in sepsis and fatal outcome of severe sepsis." (PMID 19941661, 2009).
Sepsis (continued). "Moreover, MIF’s signaling pathways also promote cellular proliferation and inhibit apoptosis, further exacerbating the inflammatory response and tissue damage associated with sepsis." (PMID 39858896, 2025). "Recently, a meta-analysis showed that blood MIF levels could have diagnostic ability to differentiate between infectious and noninfectious systemic inflammation and could have a bad prognostic value for the outcome of sepsis." (PMID 35464430, 2022). "Indeed, lethal sepsis induced in mice by lipopolysaccharide (LPS) or E. coli causes increased mortality in the presence of recombinant MIF, while anti–MIF neutralizing antibodies were able to protect mice from lethal endotoxic sepsis induced by bacterial (E. coli) peritonitis." (PMID 25503271, 2014). "Notably, the role for MIF gene variants in this study of community-acquired pneumonia progressing to sepsis was found to be one of protection, with a 50% survival benefit observed in individuals with high expression MIF alleles at 30, 60, and 90 days of followup." (PMID 23853427, 2013). "In this study, we found that CSN6 induced MIF expression in macrophages in an in vitro sepsis model." (PMID 40595050, 2025). "MIF plays a critical role in many human disease conditions, including sepsis, viral infections, diabetes, and cancer." (PMID 40092999, 2025). "In an experimental model of sepsis, neutralization of MIF by anti-MIF antibodies and genetic ablation of MIF afforded protection." (PMID 40092999, 2025). "MIF promotes kidney tubular cell pyroptosis by controlling the NF-κB–NLRP3 pathway in sepsis-induced acute kidney injury." (PMID 40018047, 2025). "Using the same model in mice, CD74 ablation protected against sepsis-induced cardiomyopathy, providing further evidence that MIF promotes cardiomyopathy in sepsis." (PMID 40092999, 2025). "MIF mediates cell pyroptosis in sepsis‐induced acute kidney injury by regulating the NF‐κB/NLRP3/GSDMD signaling pathway." (PMID 41323117, 2025). "In sepsis, it has been reported that patients with significantly higher levels of MIF in plasma exhibited an increase in fatal outcomes." (PMID 40092999, 2025). "Therefore, CSN6 may be linked to MIF to induce MIF expression in macrophages in a sepsis model." (PMID 40595050, 2025). "Another important mediator in V. vulnificus-induced sepsis is macrophage migration inhibitory factor (MIF)." (PMID 39858896, 2025). "While MIF overactivation is a validated therapeutic target in sepsis, clinical utility of existing inhibitors is hindered by adverse reactions." (PMID 40518584, 2025). "Separately, macrophage migration inhibitory factor (MIF), a proinflammatory cofactor of NLRP3, antagonizes mitophagy in sepsis-associated acute kidney injury (SA-AKI)." (PMID 41026942, 2025). "This study further explored the regulatory effects of CSN6 on MIF using an in vitro macrophage model of sepsis." (PMID 40595050, 2025). "The therapeutic potential of MIF inhibition is further supported by studies demonstrating its efficacy in mitigating inflammatory diseases and sepsis-induced acute lung injury in preclinical models." (PMID 40394027, 2025). "MIF is involved in the pathogenesis of several inflammatory and autoimmune diseases, including sepsis, rheumatoid arthritis, and systemic lupus erythematosus." (PMID 41323117, 2025). "In conclusion, CSN6 appears to aggravate inflammation in macrophages in a sepsis model via MIF signaling." (PMID 40595050, 2025). "In a study published in 2021, the authors highlighted the significant role of the MIF signaling pathway in sepsis." (PMID 38745657, 2024). "Elevated MIF levels were significantly observed in sepsis and sepsis-related ARDS in humans, as well as in LPS-induced mouse models of ALI." (PMID 38745657, 2024). "The multifaced roles of the MIF and its involvement in the genesis of pathologies like sepsis, cancer, and autoimmune diseases are highlighted in the literature, rendering MIF an attractive target for drug development." (PMID 38915940, 2024).